DMTN (dematin actin binding protein)
Description:
Membrane-cytoskeleton-associated protein with F-actin-binding activity that induces F-actin bundles formation and stabilization. Its F-actin-bundling activity is reversibly regulated upon its phosphorylation by the cAMP-dependent protein kinase A (PKA). Binds to the erythrocyte membrane glucose transporter-1 SLC2A1/GLUT1, and hence stabilizes and attaches the spectrin-actin network to the erythrocytic plasma membrane. Plays a role in maintaining the functional integrity of PKA-activated erythrocyte shape and the membrane mechanical properties. Also plays a role as a modulator of actin dynamics in fibroblasts; acts as a negative regulator of the RhoA activation pathway. In platelets, functions as a regulator of internal calcium mobilization across the dense tubular system that affects platelet granule secretion pathways and aggregation. Also required for the formation of a diverse set of cell protrusions, such as filopodia and lamellipodia, necessary for platelet cell spreading, motility and migration. Acts as a tumor suppressor and inhibits malignant cell transformation.
Synonyms: DMT; EPB49
Tractability: Antibody: its Gene Ontology location is reachable by antibodies, with high confidence; UniProt places it where antibodies can reach, with medium confidence. PROTAC: its protein half-life has been measured.
Gene: Protein-coding gene on chromosome 8 (22,048,995 to 22,082,527, forward strand). Ensembl gene ENSG00000158856.
Subcellular location: Cytoplasm; Cytoplasm, cytosol; Cytoplasm, perinuclear region; Cytoplasm, cytoskeleton; Cell membrane; Membrane; Endomembrane system; Cell projection
Pathways (Reactome):
Transport of small molecules: Miscellaneous transport and binding events
Gene Ontology:
Molecular function: actin binding; protein binding; signaling receptor binding; spectrin binding; actin filament binding
Biological process: cellular response to cAMP; protein-containing complex assembly; regulation of actin cytoskeleton organization; regulation of cell shape; regulation of filopodium assembly; regulation of lamellipodium assembly; actin cytoskeleton organization; actin filament bundle assembly; cytoskeleton organization; endoplasmic reticulum tubular network organization; erythrocyte development; lamellipodium assembly; negative regulation of cell-substrate adhesion; negative regulation of focal adhesion assembly; negative regulation of peptidyl-serine phosphorylation; negative regulation of peptidyl-threonine phosphorylation; negative regulation of peptidyl-tyrosine phosphorylation; negative regulation of protein targeting to membrane; negative regulation of substrate adhesion-dependent cell spreading; positive regulation of fibroblast migration; positive regulation of wound healing; smooth endoplasmic reticulum calcium ion homeostasis
Cellular component: actin filament; cytoplasmic vesicle; cytosol; plasma membrane; platelet dense tubular network membrane; spectrin-associated cytoskeleton; actin cytoskeleton; cell projection membrane; perinuclear region of cytoplasm; cortical cytoskeleton; cytoplasm; cytoskeleton; endomembrane system; membrane; postsynaptic density; smooth endoplasmic reticulum; synapse
Genetic constraint (gnomAD): Loss-of-function variants: 27 observed, 53.55 expected, observed/expected ratio (o/e) 0.5, 90% interval 0.37 to 0.69. The upper end of that interval is the gene's LOEUF score, 0.69, which puts it in group 2 of 6, group 1 being the genes least tolerant of losing a copy. Missense variants: 449 observed, 532.06 expected, observed/expected ratio (o/e) 0.84, 90% interval 0.78 to 0.91. Synonymous variants: 221 observed, 205.48 expected, observed/expected ratio (o/e) 1.08, 90% interval 0.96 to 1.2.
Homologues: Orthologues: chimpanzee DMTN (100% identical), dog DMTN (97% identical), mouse Dmtn (96% identical), pig DMTN (96% identical), rat Dmtn (96% identical), macaque DMTN (94% identical), guinea pig DMTN (86% identical), rabbit DMTN (85% identical), tropical clawed frog dmtn (60% identical), zebrafish dmtn (57% identical), Drosophila melanogaster Unc-115a (26% identical), Drosophila melanogaster Unc-115b (23% identical). Paralogues in human: ABLIM1 (46% identical), ABLIM3 (37% identical), ABLIM2 (32% identical).
Diseases named in the same sentence as DMTN in open-access papers:
DMTN is named in the same sentence as 14 diseases in open-access papers, as found by Europe PMC text mining. Sharing a sentence is not in itself a finding about the gene and the disease. The quoted sentences say what the papers report.
colorectal cancer (2 papers, 2018 to 2023). A primary or metastatic malignant neoplasm that affects the colon or rectum. "Our study demonstrated that the downregulation of DMTN promoted the metastasis of colorectal cancer cells by regulating the actin cytoskeleton through RAC1 signaling activation, potentially providing a new therapeutic target to enable cancer precision medicine for CRC patients." (PMID 30514346, 2018). "Colorectal cancer (CRC) is one of the most common digestive malignant tumors, and DMTN is a transcriptionally differentially expressed gene that was identified using CRC mRNA sequencing data from The Cancer Genome Atlas (TCGA)." (PMID 30514346, 2018).
prostate carcinoma (2 papers, 2010 to 2018). A carcinoma that arises from epithelial cells of the prostate gland. "The DMTN gene maps to chromosome 8p21.1, a region that is often accompanied by the loss of heterozygosity in prostate cancer patients." (PMID 30514346, 2018). "In prostate cancer PC-3 cells, the overexpression of DMTN restores epithelioid cell morphological phenotypes." (PMID 30514346, 2018).
autoimmune thyroid disease (1 paper, 2025). Inflammatory disease of the thyroid gland due to autoimmune responses leading to lymphocytic infiltration of the gland. "Low DMTN expression was enriched in immune‐related pathways, including antigen processing and presentation, autoimmune thyroid disease, cytosolic DNA sensing, natural killer cell‐mediated cytotoxicity, autophagy control, and RIG‐I‐like receptor signaling." (PMID 41316541, 2025). "Notably, diminished DMTN expression was enriched in immune‐related pathways, including antigen processing and presentation, autoimmune thyroid disease, cytosolic DNA sensing, natural killer cell‐mediated cytotoxicity, autophagy control, and RIG‐I‐like receptor signaling." (PMID 41316541, 2025).
Autoimmunity (1 paper, 2025). The occurrence of an immune reaction against the organism's own cells or tissues. "DMTN dysregulation may thus facilitate the disruption of self‐tolerance and the onset of autoimmunity in patients with SLE." (PMID 41316541, 2025).
glioblastoma multiforme (1 paper, 2023). "DMTN (Dematin Actin Binding Protein), one of the top downregulated genes, was recently identified as a vital tumor suppressor in glioblastoma multiforme, which significantly suppressed tumor growth in vivo." (PMID 36671500, 2023).
cancer (2 papers, 2010 to 2018). A tumor composed of atypical neoplastic, often pleomorphic cells that invade other tissues. "Some studies have shown that the dysregulation and deletion of DMTN are closely related to the carcinogenesis and metastasis of cancer." (PMID 30514346, 2018). "In this study, we uncovered a novel functional role for DMTN in regulating the invasion and metastasis of CRC, which might provide a new therapeutic target enabling cancer precision medicine for CRC patients." (PMID 30514346, 2018).
tumor (2 papers, 2018 to 2023). "The results from the orthotopic mouse metastatic model showed that the overexpression of DMTN decreased tumor numbers and the frequency of liver metastasis (P < 0.05), and DMTN overexpression also extended the overall survival time of the nude mice injected with the CRC cell lines (P < 0.05)." (PMID 30514346, 2018). "Furthermore, the overexpression of DMTN inhibited the invasion and metastasis of CRC cells, while the knockdown of DMTN promoted tumor invasion and metastasis." (PMID 30514346, 2018). "However, fewer reports have addressed the effect of DMTN dysregulation on the invasion and metastasis of tumor cells." (PMID 30514346, 2018). "Our results showed that the overexpression of DMTN inhibited the migration and metastasis of CRC cells, while the knockdown of DMTN promoted tumor cell migration and metastasis." (PMID 30514346, 2018).
DMTN also shares sentences with these, for which no sentence is quoted: breast carcinoma (1 paper); COVID-19 (1); iron deficiency (1); meningioma (1); neurofibromatosis (1); prostate adenocarcinoma (1); prostate tumors (1).